ENSG00000283149 (novel protein)
Gene: Protein-coding gene on chromosome 3 (186,581,995 to 186,597,103, forward strand). Ensembl gene ENSG00000283149.
Genetic constraint (gnomAD): Loss-of-function variants: 4 observed, 11.29 expected, observed/expected ratio (o/e) 0.35, 90% interval 0.17 to 0.81. Missense variants: 118 observed, 144.03 expected, observed/expected ratio (o/e) 0.82, 90% interval 0.7 to 0.95. Synonymous variants: 42 observed, 51.46 expected, observed/expected ratio (o/e) 0.82, 90% interval 0.64 to 1.06.